Y_RNA (Y RNA )
Gene: Miscellaneous RNA gene on chromosome 2 (25,697,076 to 25,697,188, reverse strand). Ensembl gene ENSG00000201160.
Homologues: Orthologues: chimpanzee Y_RNA (100% identical), macaque Y_RNA (97% identical), dog Y_RNA (85% identical), guinea pig Y_RNA (82% identical). Paralogues in human: RNY1 (83% identical), RNY1P11 (83% identical), Y_RNA (83% identical), Y_RNA (82% identical), Y_RNA (81% identical), RNY1P8 (80% identical), Y_RNA (80% identical), Y_RNA (79% identical), Y_RNA (78% identical), RNY1P10 (77% identical), RNY1P12 (77% identical), RNY1P5 (77% identical), and 95 more.